IL1B (interleukin 1 beta)
Diseases named in the same sentence as IL1B in open-access papers (continued):
Sharing a sentence is not in itself a finding about the gene and the disease.
Obesity (continued). "Dietary saturated fatty acids (SFAs), whose intake is strongly associated with an increased risk of obesity, have been identified as potent priming agents of the NLRP3 inflammasome via TLR4 in DCs, resulting in elevated expression of pro-IL-1β, caspase-1, TLR4 and NLRP3." (PMID 32545355, 2020). "Studies show that HFD-induced obesity increases expression of the pro-inflammatory cytokine interleukin-1 beta (IL-1β) and induces insulin resistance in the amygdala through increased activation of the pro-inflammatory transcription factor nuclear factor-kappa B (NF-κB)." (PMID 33574742, 2020). "In addition, the consumption of green tea reduced the imbalanced production of cytokines such as TNF-α, IL-1β, and IL-6 in the cortex, cerebellum, and brainstem in obesity-induced mice." (PMID 33312340, 2020). "However, ST2 deficiency did cause significant reductions in serum IL-1β, TNFα, and CCL5 in the HFD-fed mice, suggesting that IL-33 contributes to aspects of the systemic inflammation of obesity." (PMID 32326950, 2020). "In general, GF mice are resistant to HFD-induced obesity, produce lower levels of inflammatory cytokines including TNFα, IFNγ, IL-1B, and IL-17, and have blunted transcriptional oscillations of the core clock gene Bmal1 relative to conventionally-raised specific pathogen-free (SPF) mice." (PMID 33255707, 2020). "We also found increased concentrations of CCL3, IL-1β, and TNFα from among the 38 cytokines, chemokines, and growth factors examined in plasma from ccRCC subjects with obesity versus tumor-free donors with obesity." (PMID 32469992, 2020). "An involvement of TNFα and IL-1β in the activation of YAP and TAZ in mouse adipocytes during obesity could be demonstrated by treating animals with the TNFα inhibitor etanercept and the IL-1β inhibitor anakinra." (PMID 33116140, 2020). "Collectively, our data identify enhanced glycolysis and HIF-1α activation in ATM as key mechanisms underlying macrophage persistence in the WAT and the local and systemic expression of IL-1β, placing these immunometabolic signals at the interface of macrophage activation in obesity." (PMID 32221369, 2020). "Interestingly, in both genetic models of obesity, the levels of most of the microglial activity markers are lower than in wild type mice, whereas IL1β is lower also in comparison with HFD obese mice." (PMID 32106469, 2020). "Further, NF-κB is a critical transcription factor of M1 macrophages, regulating the expression of a variety of inflammatory genes, including those encoding IL-6, IL-1β, MCP-1, and cyclooxygenase-2 (COX-2), shown to play important roles in obesity-related PDAC promotion." (PMID 31277269, 2019). "Interestingly, the results of this meta-analysis suggested that polymorphisms in the adipokine genes, ADIPOQ, IL-1β, IL-6, and TNF-α, increase the risk of obesity." (PMID 31354816, 2019). "However, ABG treatment attenuated the obesity-induced increase in the gene expression of IL-1β (p < 0.01), TNF-α (p < 0.05) and iNOS (p < 0.01)." (PMID 30642033, 2019). "IL-1β contributes to the pro-inflammatory response in obesity." (PMID 31174550, 2019). "AT macrophages (ATM), which can account for up to 50% of the cellular content in the obese AT, are the primary source of pro-inflammatory cytokines (e.g., IL-6, TNF-α, IL1-β), and have been shown to be centrally important in obesity-related metabolic dysfunction." (PMID 31277269, 2019). "This production of CD11c+ ATMs could also feed-forward to enhance the IL-1β signaling induced by S100A8/A9 in obesity to promote myelopoiesis and monocytosis." (PMID 31249530, 2019).
Obesity (continued). "It is therefore likely that IL-1β signaling from ATMs could also potentiate trained immunity within the context of obesity and that S100A8/A9 may therefore play a role in trained immunity upstream of IL-1β." (PMID 31249530, 2019). "IL-1β is produced mostly by adipose tissue macrophages and its release is increased in obesity." (PMID 30360437, 2018). "Differential mRNA levels for leptin, IP-10 and IL-1β with 12- and 28-weeks of diet-induced obesity." (PMID 29527173, 2018). "Inhibition of IL-1β expression attenuates severity of hyperglycaemia in obesity." (PMID 30429827, 2018). "Obesity was positively correlated with increases in viral RNA quantities, whereas negative associations were observed for IL-1β and IP-10 levels." (PMID 29581859, 2018). "Furthermore, the obesity-induced upregulation of IL-12 and IL-1β genes were also suppressed by both doses of HK L-137." (PMID 29802339, 2018). "Our data suggests that HFD may rapidly induce airway hyperresponsiveness prior to the development of significant obesity with early involvement of IL-1β." (PMID 29686414, 2018). "Obesity, particularly visceral, is strongly associated with dysregulated expression of inflammatory cytokines such as tumor necrosis factor-alpha (TNF-α), interleukin-1 beta (IL-1β), and IL-6, as well as adiponectin and leptin, contributing to metabolic derangement and insulin resistance." (PMID 29910818, 2018). "Although some cytokines such as TNFα and IL1β reduce adipose Lipin-1 expression, the mechanism by which the expression of Lipin-1 was impaired in adipose tissue in obesity states remains unclear." (PMID 29534036, 2018). "It has been suggested that obesity-related inflammatory cytokines, including tumor necrosis factor α (TNFα), interleukin-1β (IL-1β) and IL-6, may accelerate muscle catabolism." (PMID 29949600, 2018). "Obesity is associated with chronic low-grade inflammation of white adipose tissue (WAT), in which there is upregulated secretion of the pro-inflammatory cytokines TNF-α, IL-1β and IL-6." (PMID 27840174, 2017). "In fact, IL-6 and IL-1β are positive modulators of insulin resistance in adipose tissue and the heart during obesity, which might be of medical interest." (PMID 29201273, 2017). "Thus, reciprocal amplification of IL-1β and Th17 cytokines in adipose tissue appeared critical to sustain local inflammation and systemic glycemic deterioration in human obesity." (PMID 28592801, 2017). "Many studies have shown that IL-1β blockers, such as anti-IL-1β monoclonal antibody, specifically block the inflammatory signaling cascade, which provides an effective treatment for obesity-related inflammation, insulin resistance, type II diabetes, and autoimmune diseases, like type I diabetes." (PMID 28182687, 2017). "As demonstrated, IL-1β is a quintessential pro-inflammatory cytokine associated with obesity and metabolic disorders, and MCP-1 accelerates macrophage infiltration in inflammation accompanying obesity." (PMID 28545248, 2017). "A recent report suggested that nucleotide-binding domain, leucine-rich containing family, pyrin domain-containig-3 (Nlrp3) inflammasome plays a pivotal role in obesity-induced chronic inflammation, and Nlrp3 inflammasome activates caspase-1, which induces the secretion of IL-1β." (PMID 28569167, 2017). "We extended this exploration to pre-adipocytes, CD31+ endothelial cells and mature adipocytes, focusing on a set of inflammation-related genes (CCL2, CCL20, IL-8, IL-6 and pro-IL-1β) selected among genes known to be up-regulated in adipose tissue with human obesity." (PMID 28592801, 2017). "Indeed, multiple studies have demonstrated that inflammasome activation and the cleavage of inflammatory cytokines IL-1β and IL-18 induced by obesity in key metabolic tissues promote chronic inflammation and contribute to the development of T2D." (PMID 29096724, 2017).
Obesity (continued). "Indeed, our group has demonstrated increased IL-1β gene expression in 3T3-L1 murine adipocytes stimulated with low-dose LPS to mimic in vivo circulating levels in obesity." (PMID 29186929, 2017). "Supporting these findings in the context of obesity and diabetes, Osborn and colleagues observed significantly reduced HbA1c levels when they treated mice suffering from T2D with anti-IL-1β antibodies, which indicates a beneficial effect on glucose tolerance and/or insulin resistance." (PMID 28299341, 2017). "Furthermore, the low-grade chronic inflammation of the obesity caused by the HFD was also attenuated after PTE treatment, as demonstrated by the reduction of IL-1β expression level." (PMID 29056891, 2017). "Two obesity-related cytokines were measured at endpoint: adiponectin and IL1b." (PMID 29271886, 2017). "We had thus reasoned that the NLRP3 inflammasome is required for IL-1β production under obesity." (PMID 27708283, 2016). "We also examined molecular pathways associated with adipose inflammation, which has been shown to mediate obesity-related cancer and found the proinflammatory gene IL-1β (IL1B) to be hypermethylated in high vs. low BMI cases when we assessed the combined esophageal tissue sets." (PMID 27795744, 2016). "Indeed, pro-inflammatory adipokines, which are upregulated in obesity, such as IL-1α, IL-1β, and TNF-α have been described as potent PAR2 inducers in the vasculature." (PMID 28101054, 2016). "Taken together, IL-1β represents a model in which adipokines may be indirectly employed as target molecules for the treatment of obesity-related and inflammation-induced insulin resistance comorbidities as well as for some autoimmune diseases." (PMID 25918733, 2015). "IL-1β is a major contributor to the pathophysiology of obesity in pregnancy and GDM." (PMID 25849717, 2015). "Additionally neutrophils are a major site for expression of NLRP3 inflammasome components and a significant source of IL1β production, processes demonstrated to be important in obesity-induced insulin resistance." (PMID 26405763, 2015). "This notion is mainly based on the hypothesis that obesity per se increases inflammation, i.e., proinflammatory cytokines like IL-1β and IL-6 due to an increased leakiness of the gut barrier in obese individuals." (PMID 26421054, 2015). "Taken together, these data support the hypothesis that IL-1β promotes TG accumulation by upregulating denovo lipogenesis in primary hepatocytes and is important for the pathogenesis of obesity-induced steatosis." (PMID 25216251, 2014). "However, Stienstra and colleagues suggested that IL-1β-mediated suppression of hepatic PPARα and fatty acid oxidation was responsible for hepatic lipid accumulation in obesity." (PMID 25216251, 2014). "Non-alcoholic fatty liver disease is prevalent in human obesity and type 2 diabetes, and is characterized by increases in both hepatic triglyceride accumulation (denoted as steatosis) and expression of pro-inflammatory cytokines such as IL-1β." (PMID 25216251, 2014). "Thus, recent data show that NLRP3-/- knockout mice do not increase weight when fed a high fat diet, and that elimination of NLRP3 expression prevents obesity-induced caspase-1 cleavage as well as IL1β and IL18 activation." (PMID 25020064, 2014). "Animal studies showed that hepatic IL-1β protein and mRNA levels to be increased in various diet-induced NASH models in mice, while adipose specific IL1B deficiency in mice increase susceptibility to obesity." (PMID 25512222, 2014). "Thus, the decreases in hepatic inflammation after clodronate liposome-mediated KC depletion suggest that inflammasome activation required to increase IL-1β production from KCs is important for obesity-induced hepatic inflammation." (PMID 25216251, 2014). "What is IL-1β's role in adipose tissue inflammation in obesity?" (PMID 23341960, 2013).
Obesity (continued). "Moreover, the levels of macrophage M1 phenotype, MCP-1, TNF-α, IL-6, and IL-1β are elevated in obesity and insulin resistance, and these factors play a major pathophysiological role in heart failure." (PMID 24454978, 2013). "Jointly, it appears that IL-1β may mainly exert autocrine/paracrine effects in adipose tissue that consequently deteriorate metabolic adipose-liver crosstalk in obesity." (PMID 23341960, 2013). "IL-1β is a major promoter of adipose tissue inflammation in obesity." (PMID 23341960, 2013). "Collectively, we demonstrate that by promoting adipose inflammation and limiting fat tissue expandability, IL-1β supports ectopic fat accumulation in hepatocytes and adipose-tissue macrophages, contributing to impaired fat-liver crosstalk in nutritional obesity." (PMID 23341960, 2013). "It has been suggested that macrophage accumulation in adipose tissue has a central role in stimulating MMP1 and MMP3 production by preadipocytes, mediated by IL1β and TNFα, supporting the role of macrophages in stimulating tissue remodeling during adipose tissue expansion in obesity." (PMID 23497408, 2013). "Obesity causes lipotoxicity and adipose tissue dysfunction with excessive production of adipokines like tumor necrosis factor-α (TNF-α) and interleukin 6 (IL-6) IL-1β, all of which are implicated in heart failure and related cardiometabolic complications." (PMID 24454978, 2013). "Yet, it remains largely unknown if IL-1β, a cytokine believed to mainly function locally, could regulate dysfunctional inter-organ crosstalk in obesity." (PMID 23341960, 2013). "Yet, whether and how IL-1β regulates adipose inflammation and fat-liver crosstalk in obesity is poorly defined." (PMID 23341960, 2013). "Circulating IL1β and IL1Ra are elevated in patients with obesity and type 2 diabetes." (PMID 23941335, 2013). "However, of its products, the specific role of IL-1β was clinically demonstrated to mediate only the pancreatic beta-cell demise, and in mice mainly the intra-hepatic manifestations of obesity." (PMID 23341960, 2013). "Adipose tissue insulin resistance may occur in obesity in part through the infiltration of macrophages which release pro inflammatory cytokines such as TNFα, IL-6 and IL1β." (PMID 22363403, 2012). "In obesity, fat tissue is a source of IL-1 and human IL-1β rises with age." (PMID 22935594, 2012). "Obesity is associated with "low-grade inflammation", a term that is used to reflect increments in the systemic concentration of tumour necrosis factor-alpha (TNF-α), interleukin (IL)-1β, IL-6, IL-1ra, and C-reactive protein (CRP)." (PMID 21599899, 2011). "Finally, I explored therapeutic options targeting iron metabolism or inflammasome signaling, such as iron chelation, hepcidin antagonism, and interleukin-1 beta (IL-1β) blockade, as potential interventions to treat adipose tissue dysfunction in obesity and T2D." (PMID 40943225, 2025). "Furthermore, ANGPTL4 may interact with other inflammatory mediators as demonstrated in obesity-related breast cancer, e.g., by the upregulation of IL-1β in inflammatory conditions." (PMID 40006981, 2025). "Furthermore, chronic stimulation of beta cells by IL-1β may promote unprocessed proinsulin secretion with subsequent obesity and diabetes." (PMID 39496966, 2025). "Specifically, it downregulates pro-inflammatory cytokines (e.g., TNF-α, IL-1β, and IL-6) while upregulating anti-inflammatory IL-10 and tight junction proteins (e.g., ZO-1 and OCLN), thereby reducing systemic inflammation and metabolic endotoxemia associated with obesity." (PMID 41365537, 2025). "However, since IL1β is a crucial player in initiating and maintaining tissue damage, it is possible that, in children and adolescents with obesity, its levels are higher systemically, and when liver damage begins to progress, IL1β is more present locally in the target tissues." (PMID 40004960, 2025).
Obesity (continued). "Here we demonstrated that oral administration of C.B effectively alleviated HFD-induced obesity and associated metabolic disorders, including glucose intolerance and hyperlipidemia, as well as systemic inflammation, as evidenced by reduced levels of LPS, TNF-α, and IL-1β." (PMID 40415947, 2025). "Furthermore, obesity is associated with chronic inflammation and elevated levels of cytokines, such as TNF-α, interleukin-1 beta (IL-1β), interleukin-6 (IL-6), and adipokines (e.g., leptin), which support tumor cell proliferation, angiogenesis, and TME modulation." (PMID 41228278, 2025). "Therefore, a sustained increase in the expression of IL-1β in adipose tissue during obesity could play a critical role in the development of IR." (PMID 41154464, 2025). "Intriguingly, despite clear evidence that NLRP3 inflammasome and IL-1β activity drive obesity and MAFLD, whether pyroptosis or other modes of programmed cell death, such as apoptosis and necroptosis, facilitate the demise of key cell types in tissues remains ambiguous." (PMID 39532538, 2025). "Of note, it is essential to highlight that the use of cytokines as biomarkers of MASLD may face some critical challenges in the clinical context: (a) many cytokines implicated in MASLD, such as IL-1β, TNF-α, and IL-6, are also involved in obesity, IR, and T2DM, which usually coexist with MASLD." (PMID 40794228, 2025). "Elevated levels of interleukin-1β (IL-1β) and tumor necrosis factor-α (TNF-α), part of the inflammatory network linking these two conditions, persist even after periodontal treatment, with high salivary cytokine levels being linked to overweight and obesity risk." (PMID 40430061, 2025). "Furthermore, in mice models, IL-1β signaling increases hepatic lipogenesis and steatosis by upregulating fatty acid synthase, thus highlighting the link between non-alcoholic fatty liver disease and obesity." (PMID 38257150, 2024). "In addition, a considerable reduction in obesity-associated low-grade chronic inflammation (TNF-α, IL-6, IL-1β plasma levels) could be observed." (PMID 39765824, 2024). "The results showed a significant association (P < 0.05) between NASH- and obesity-related parameters and the gut microbiota of GAN-fed mice, including body weight, total fat, TC, LDL, AST, liver weight, NAS, steatosis, lobular inflammation, hepatocyte ballooning, TNF-ɑ, IL-1β, and IL-6." (PMID 38018983, 2024). "Compare people with significant differences in obesity degree, a total of 25 miRNAs have been identified as targeting three upregulated adipogenesis-associated inflammatory genes, namely interleukin-6 (IL-6), tumour necrosis factor-alpha (TNF-α), and interleukin-1 beta (IL-1β)." (PMID 38982993, 2024). "In addition, the volunteers with obesity showed higher ratios between IL-1β and IL-10 (A, p < 0.0001), IP-10 and IL-10 (D, p < 0.05), TNF-α and IL-10 (E, p < 0.0001), IL-12p70 and IL-10 (F, p < 0.01), IFN-γ and IL-10 (G, p < 0.05), and GM-CSF and IL-10 (H, p < 0.0001) than the NW group." (PMID 39125408, 2024). "It is established that obesity is associated with a state of chronic inflammation in the patient, characterized by the accumulation of M1-polarized macrophages, Tregs, and the secretion of proinflammatory factors, including TNF-α, IL-6, IL-1β, and leptin, which have all been linked to CRC." (PMID 39201522, 2024). "In contrast to IL6, IL1B is not up-regulated in the IFP of end-stage KOA patients which can explain why our study could not find any correlation between obesity-linked systemic factors and IL1B gene expression." (PMID 38694906, 2024). "Furthermore, upregulation of the NLRP3 and IL-1β genes can influence upon chronic inflammation, potentially affecting the function of the endocrine system, possibly contributing to metabolic problems such as obesity, insulin resistance and diabetes." (PMID 39264098, 2024). "Similarly, IL-1β release is enhanced in the visceral depot in obesity." (PMID 37189813, 2023).